CD44 (CD44 molecule (IN blood group))
Diseases named in the same sentence as CD44 in open-access papers (continued):
Sharing a sentence is not in itself a finding about the gene and the disease.
tumor (continued). "For example, nanoparticles decorated with HA could be a potential delivery system for anticancer drugs to target tumor cells overexpressing the CD44 transmembrane receptor, thus reducing the side effects of conventional therapies." (PMID 38672482, 2024). "Likewise, computational network analysis of mouse scRNA-seq data suggests Spp1/Cd44 as one pair of top predicted genes of ligand-receptor interaction in tumor ECs-2 and Mφs, respectively." (PMID 38416830, 2024). "Hyaluronic acid (HA)-modified nanoliposomes effectively target CD44-overexpressing tumor cells." (PMID 38337294, 2024). "Moreover, MIF-(CD74 + CD44) signaling between fibroblasts and cholangiocytes, dendritic cells and T cells was significantly enhanced in tumor tissue." (PMID 38702814, 2024). "Additionally, the stem cell marker CD44 is consistently and predominantly coexpressed in these cell clusters, suggesting that these cells are cancer stem cells that contribute to tumor recurrence." (PMID 39020106, 2024). "In addition to CD44, the ALDH1 enzyme has also been extensively linked to the CSC phenotype in tumour cells, given its versatility in roles such as detoxification, protection against oxidative stress, retinoid metabolism, and tissue development." (PMID 38719848, 2024). "Importantly, treatment of MC38 tumor-derived TILs with the SMAD3 inhibitor (E)-SIS3 significantly enhanced the expression of effector cytokines in CD44+CD8+ T cells, confirming the critical role of SMAD3 activation in suppressing memory CD8+ T cell function." (PMID 38971819, 2024). "Thus, TME acidification and the consequent alteration in CD44-mediated cellular interactions provide another example linking glycosylation with cancer progression and tumor metastasis." (PMID 39123480, 2024). "Invitro, we found that CS at a specific concentration could increase thediameter and number of 786-O and ACHN tumor spheres, and the expression level ofRCSCs markers (CD44, Oct4, SOX2) was significantly increased." (PMID 38985013, 2024). "Similar investigations comparing tumor and non-tumor tissue associated CD44 expression with tumor invasion, metastasis, progression, treatment resistance, and poor overall survival." (PMID 38727811, 2024). "Often, they exploit the HA affinity for CD44, which is highly expressed in tumor cells." (PMID 38543324, 2024). "However, the direct attachment of HA onto SERS‐NPs failed to produce significant targeting of the biological receptor, CD44 protein, overexpressed on tumor cells." (PMID 39185268, 2024). "Overexpression of CD44 is also evident in analyzed tumor samples from patients." (PMID 38796656, 2024). "In addition, there was no tumor recurrence when CT26 tumor cells were inoculated into tumor clearance mouse species, and it is due to the adaptive immunity by CD44+/CD62Llow memory T cell." (PMID 39769944, 2024). "CD24 and CD44 have been regarded as negative prognostic factors for MSGTs, associated with increased tumor size, positive lymph nodes, and advanced clinical stage." (PMID 39858584, 2024). "CD44 was previously found to modulate energy metabolism in tumor cells." (PMID 38287411, 2024). "CD44 is a cell adhesion molecule involved in tumor growth and biological behavior." (PMID 38255201, 2024). "High CD44 expression reflects the aggressiveness of tumor cells and the malignancy of HNSCC." (PMID 38355684, 2024). "The tumor weights of the three groups of CD133+CD44+ cells were significantly different (P < 0.05)." (PMID 38967742, 2024). "Additionally, cell fluorescence experiments demonstrated that overexpression of Circ-0075305 significantly inhibited the growth of GC tumor spheres and downregulated the expression of CD44 and NANOG compared to the control group." (PMID 38714724, 2024).
tumor (continued). "Indeed, CD44-positive cells were found to promote the secretion of high level of osteopontin (OPN) by macrophages, which in turn binds to CD44 expressed by tumor cells promoting clonal growth via the activation of the JNK pathway, invasion and metastasis." (PMID 38600583, 2024). "This suggests that the co-expression of CD44 & CD133 could be regarded as a stand-alone prognostic molecular marker indicative of tumor stemness." (PMID 38706601, 2024). "The L–Rs including the MIF-(CD74+CXCR4) and collagen/fibronectin/laminin-CD44 interactions in MTs may create a tumor immunosuppressive microenvironment." (PMID 38414027, 2024). "It suggested that OPN and CD44 in protein coronas, as typical proteins related to adhesion and uptake of tumor cells, may promote nanovesicle internalization through OPN-integrin and CD44-mediated ligand-receptor binding." (PMID 38326312, 2024). "PCSC implanted into NOD/SCID mice could reconstruct tumor cell subsets and express CD44, CD133 and CD166 in different proportions." (PMID 39668824, 2024). "Moreover, the cell surface adhesion molecule CD44 complexes with Ezrin to enhance tumor cell adhesion and invasion when co-localized in PCa-endothelial cells, facilitating tumor progression." (PMID 39055653, 2024). "HA exhibits a high affinity for CD44 overexpressed on tumor cells." (PMID 39513925, 2024). "To assess whether TSG-6 plays a role in the distinct macrophage phenotypes seen in the two tumor models, we examined the expression of Cd44, the only known ligand of TSG-6, across all immune cells." (PMID 38987547, 2024). "In the TDLNs, all administrations of RZ activated DCs on D15, but on D20, the proportion of mDCs in the RZ (s.c.)and RZ (i.t.)groups decreased, while the RZ‐BPH group remained a high level of mDCs, increasing effector memory T cells (TEM, CD3+CD8+CD44+CD62L–) in the tumor." (PMID 38308098, 2024). "Furthermore, Clay and colleagues demonstrated that ALDH+ cancer cells isolated from a primary OSCC tumor were ten times more tumorigenic than CD44+-only cells, strongly supporting the use of ALDH as a more discriminatory marker for CSCs in HN-/OSCC." (PMID 39335624, 2024). "The tumor-promoting effects of POLE2 were alleviated by downregulating CD44 expression." (PMID 38627379, 2024). "In addition, a decreased frequency of tumor-infiltrating effector memory cells (CD44+CD62L−) was observed among adoptive CD45.2+ OT-I CD8+ T cells from Id2fl/flCd4-Cre+ OT-I mice compared to Id2fl/flCd4-Cre− OT-I mice." (PMID 38287103, 2024). "Furthermore, the Bulk Tumor, Proliferating, and CD44 Immune CNs, which particularly compose the TLSs evident within 2 cores (1 patient) of the 5-year survival cohort, are enriched albeit not significantly." (PMID 39333065, 2024). "Upregulation of BRMS1 in microglia may lead to M2 macrophage polarization, activate the PI3K/AKT signaling pathway through SPP1/CD44-mediated cell interactions, inhibit tumor cell apoptosis, and promote tumor proliferation and invasion." (PMID 39143438, 2024). "We aimed to determine if ALDH1A1 or CD44 could provide clinically relevant tumor-specific prognostic information to aid in counseling patients and direct potential management with ALDH1A1 targeted treatment." (PMID 38371078, 2024). "Thebrownish area in CD44 IHC slide was co-localized with the dense nucleusstain area in H&E slide, indicating CD44 expression in tumor area.The extensive blue color observed in Prussian blue staining indicatedthe presence of NP-ICG-HA in metastatic sites in lungs." (PMID 38757711, 2024). "In interactions with epithelial cells, the binding of MIF to CD74 and CD44 may affect cell proliferation, migration, and functions in pathological states, such as promoting tumor cell growth and metastasis in the tumor microenvironment." (PMID 38720887, 2024). "Interestingly, KO/KD of either iRhom1 or iRhom2 decreases CD44 cleavage and further improves the CD44-mediated tumor targeting of NPs likely through decreasing the activity of ADAM17." (PMID 38177179, 2024).
tumor (continued). "In neoplastic diseases therapeutic areas, it is very crucial to clarify the mechanism of CD44 in the signaling pathways, thereby delaying, treating, and preventing the development of tumors through targeting CD44." (PMID 38783892, 2024). "As an extracellular matrix protein, FN1 binding to CD44 may influence the invasive and metastatic capabilities of tumor cells." (PMID 39456726, 2024). "Previous studies had found that SPP1 involved in tumor progression by interacting with CD44." (PMID 38346944, 2024). "Additionally, CAFs strongly expressed COL6A and COL1A family genes, which interact with CD44 and were widely present in the tumor stage." (PMID 39456726, 2024). "We further investigated the percentage of Tem (CD44+CD62L−) in tumor tissues via flow cytometry." (PMID 39021327, 2024). "Additionally, AP-2α mediates the anti-tumor effects of small ubiquitin-like modifier (SUMO) inhibitors by downregulating CD44 and MMP14, restraining tumor stemness." (PMID 39273087, 2024). "The spheroids in this system displayed characteristics of CSCs with the formation of a tumor when xenografted, overexpressed CSCs markers such as CD44, and increased resistance to cisplatin, rendering this system useful for the screening of CSC-targeting drug candidates." (PMID 39335624, 2024). "Therefore, an in-depth study of the function of CD44 and its mechanism of action in different tumor types is of great significance in promoting the development of precision medicine and cancer treatment strategies." (PMID 39184916, 2024). "Different isoforms of CD44 participate in regulating various signaling pathways, modulating cancer proliferation, invasion, metastasis, and drug resistance, with its aberrant expression and dysregulation contributing to tumor initiation and progression." (PMID 38783892, 2024). "Importantly, tumor cells tend to express CD44 constitutively in the active state with capacity for high-affinity HA binding." (PMID 38542421, 2024). "Overall, high expression of CD44, regardless of isoforms, is mainly positively associated with the development of neoplastic disease." (PMID 38783892, 2024). "This review provides up‐to‐date information about the roles of CD44 in neoplastic diseases, which may open new perspectives in the field of cancer treatment through targeting CD44." (PMID 38783892, 2024). "Furthermore, the influence of substrate stiffness on CD-44 expression was investigated, by culturing both healthy and tumour cells on stiff substrate mimicking the tumour microenvironment." (PMID 38172135, 2024). "Given the regulatory effect of CALCR on CD44 expression, we further explored whether the tumor promotion of CALCR required CD44 expression." (PMID 38985127, 2024). "CD44 overexpression was also associated with clinically poor prognostic features: older age, inoperable disease, stage IV at diagnosis, mutated BRAF, and high-grade tumor." (PMID 38672650, 2024). "In the Pan-Cancer Atlas, HNSCC has been shown as the second-highest CD44-expressing tumor type." (PMID 39273139, 2024). "In fact, CD44 expression correlates with increased tumor aggressiveness and metastasis generation." (PMID 38791253, 2024). "PTEN mutation can induce an immunosuppressive tumor microenvironment, which is not derived from traditional Treg cells but from tumor cells overexpressing CD44." (PMID 39206155, 2024). "Only CD133+CD44+ cells produced abundant tumor spheres in vitro, suggesting that they were CCSCs." (PMID 38468952, 2024). "In contrast to integrin VLA-4, CD44 can interact with integrin α6β4 to form a complex, which activate intracellular cytoskeletal proteins and their signaling pathways, thereby modulating the c-Src and Ras signaling cascade and promoting tumor cell migration." (PMID 38736891, 2024). "OPN and CD44 as important components of protein coronas formed in tumor environment, may play important roles in cellular uptake of nanovesicle in tumor cells." (PMID 38326312, 2024).
tumor (continued). "Further, CD44 is expressed by non-tumor cells, including hematopoietic progenitors, which may pose challenges in clinical translation." (PMID 38414005, 2024). "The role of CD44 in tumor immunomodulation cannot be underestimated." (PMID 38590654, 2024). "TAMos derived from spleens of LLC tumor‐bearing mice markedly enhanced TCM cell differentiation as indicated by elevated percentages of CD44+CD62L+ T cells and increased levels of CD62L, CCR7, and IL‐7R expression during T cell antigen‐specific activation compared with vehicle or TANs." (PMID 38386350, 2024). "Therapies, such as the inhibition of CD44-HA interactions, could potentially reduce stem-like properties, limit tumor growth, and enhance the efficacy of existing treatments." (PMID 39518076, 2024). "Moreover, OPN promotes stem cell-like proprieties and radiation resistance in adjacent tumor cells via activation of CD44 signalling." (PMID 38600583, 2024). "Consistent with the development of a CD8+ T cell-mediated memory response, splenic CD8+ cells from mice treated with atovaquone plus aPD-L1 experiencing durable tumour eradication showed increased levels of T cell activation markers (CD44, PD-1) when challenged ex vivo with CT26 cells." (PMID 38212297, 2024). "A major component of the stroma in PDAC, hyaluronic acid (HA), interacts with cell surface receptors CD44 and receptor for HA-mediated motility (RHAMM) to promote tumour cell survival and to initiate signalling pathways associated with tumour cell proliferation, migration, and invasion." (PMID 38384463, 2024). "In addition, previous studies showed that HA/CD44 promotes cancer cell proliferation and tumor progression." (PMID 39039104, 2024). "Furthermore, CD44 expression has been noted in metaplasia, suggesting a possible role in tumor progression." (PMID 39547513, 2024). "In addition, immunohistochemistry of tumor nodules showed that the knockdown of SIX4 decreased the expression of CD44 and CD133." (PMID 39309424, 2024). "The interaction between HA and its receptor CD44, together with the excellent HA biocompatibility, biodegradability, and nonimmunogenicity, has also been exploited to increase the delivery of conventional antineoplastic drugs into tumor cells." (PMID 37953485, 2024). "These include the binding of CD44 on OC cells to the glycosaminoglycan hyaluronan on mesothelial cells, even though hyaluronic acid secreted by mesothelial cells has also been suggested to provide a barrier to tumor cell adhesion." (PMID 38566518, 2024). "Here, we examined the expression of CD44 in tumor cell lines and in patients’ material." (PMID 38796656, 2024). "Animals treated with ADU-S100 + anti-ISG15 had a significant increase in the frequency of tumor infiltrating CD62L+CD44+ central memory CD8+ and CD4+ T cells compared to those treated with ADU-S100 alone, as well as an increase in CD44+CD62L- effector CD4+ TIL." (PMID 38312842, 2024). "Furthermore, tumor cells can secrete multiple ligands of CD44, including osteopontin and hyaluronic acid, to regulate the homing, activation, maturation, and proliferation of immune cells." (PMID 37138324, 2023). "We and others have previously proved that upregulation of stemness and EMT-related markers could confer tumor cells with CSC-like properties, and CD44+/CD24−/low cells were widely used to characterize the BCSC populations or tumor-initiating cells." (PMID 36633714, 2023). "A growing body of evidence reveals the critical roles of CD44 in tumor progression and metastasis." (PMID 37176118, 2023). "The fact that a high percentage of OE-S-2HG-treated OT-I cells were preserved in a TCM (CD44+/CD62L+) phenotype within the tumor might explain the decreased anergy we observed when restimulating these cells in vitro." (PMID 37632752, 2023). "Moreover, the targeting capacity added by CD44 targeting HA enhanced the attachment and retention of these nanoparticles at the tumor site." (PMID 37283735, 2023).
tumor (continued). "Experiments blocking CD44 on monocytes by HA addition diminish their reaction to tumor cells." (PMID 37107200, 2023). "In contrast, expression of the tumor stem cell marker Cd44 was MALAT1-independent." (PMID 37325561, 2023). "CD44 participates in the immune escape of tumor cells may be achieved by affecting CTLA-4 on T cells." (PMID 37316699, 2023). "The CD44-ECD in the synNotch receptor acts as a CD44 decoy receptor in the tumor microenvironment (TME), and after a ligand binds to the CD44-ECD, HIF-3α4 is released from the Notch core regulatory region at the cell membrane to inhibit the hypoxia-induced responses." (PMID 37064130, 2023). "CD44 plays a major role in both tumor neoangiogenesis and progression because of its affinity for messengers, such as growth hormones present in the tumor microenvironment as well as extracellular matrix elements including hyaluronan (HA) and osteopontin (OPN)." (PMID 37887005, 2023). "Moreover, the action of CD44 on tumor cells was identified as being a negative regulator of “in-cell killing” via its inhibition of CIC formation." (PMID 37511762, 2023). "Since we have already cloned the VH and VL cDNA of anti-CD44 mAbs, the production of recombinant mAbs or CARs could contribute to the development of novel tumor therapies." (PMID 37504249, 2023). "Thus, APN KO BMSCs highly migrate toward EL-4 tumor mass by CD44-HA interaction and recruit CD8+ T cells by releasing of CCL8." (PMID 37370133, 2023). "PPI network analysis revealed that CD44 may play a key role in cell adhesion, tumor growth, drug resistance, cell differentiation, EMT, T cell activation, and immune function." (PMID 37316699, 2023). "The data obtained consistently indicate an over-expression of CD44 in numerous tumor types." (PMID 37491225, 2023). "Hyaluronic acid (HA), a natural glycosaminoglycan is a commonly used ligand that binds receptors such as clusters of differentiation-44 (CD44) that are over-expressed by tumor cells and involved in drug delivery for tumor, tissue engineering and joint diseases." (PMID 36850121, 2023). "Given the high targetability of HA to CD44 expressing cancer cells, the obtained HA-zein NPs could enter tumor cells effectively via a CD44 mediated endocytosis thereby enhancing the PK/PD." (PMID 36817160, 2023). "It is noteworthy that the capability of CD44 to bind with extracellular matrix components and hyaluronic acid allows cancer stem cells (CSCs) to receive and perceive signals and alterations in the tumor environment." (PMID 37491225, 2023). "After 21 days, CD44-ve cells showed significantly increased tumor sizes (P = 0.013)." (PMID 37523119, 2023). "The expression of CD44 is more frequent in circulating tumor cells than in brain metastasis." (PMID 36895477, 2023). "Targeting CD44 to accumulate inside tumor cells via HA conjugation." (PMID 36826291, 2023). "Furthermore, the CSC marker CD44 was also upregulated in tumor lesions, while Numb showed a positive correlation with YY2." (PMID 37300334, 2023). "Interestingly, CD44 can also act as a tumor suppressor under confluent growth conditions, where binding with hyaluronate leads to activating and binding with Merlin, subsequently conferring growth arrest and contact inhibition." (PMID 37371090, 2023). "A relevant panel would include CTC to measure residual tumor burden, circulating erythroid cells to measure bone marrow damage, circulating endothelial cells to measure vascular damage and recovery, and CD44+ cells to measure a general cellular state of activation." (PMID 36100762, 2023). "Additional CD44 tumor-promoting functions might be revealed when interfering with CD44 function later in the development." (PMID 37174657, 2023). "Furthermore, compared to the sh-NC group, downregulation of hsa_circRNA_001676 led to significant decreases in CD133, CD44, Oct-4 and Nanog levels in tumor tissues." (PMID 37884630, 2023).